IREB2 (iron responsive element binding protein 2)
Description:
RNA-binding protein that binds to iron-responsive elements (IRES), which are stem-loop structures found in the 5'-UTR of ferritin, and delta aminolevulinic acid synthase mRNAs, and in the 3'-UTR of transferrin receptor mRNA. Binding to the IRE element in ferritin results in the repression of its mRNA translation. Binding of the protein to the transferrin receptor mRNA inhibits the degradation of this otherwise rapidly degraded mRNA.
Synonyms: IRE-BP 2; IRP2; ACO3; IRE-BP2; IRP2AD; NDCAMA
Tractability: Small molecule: a structure with a bound ligand is known. PROTAC: UniProt records ubiquitination sites on it; ubiquitination databases record sites on it; its protein half-life has been measured.
Gene: Protein-coding gene on chromosome 15 (78,437,431 to 78,501,453, forward strand). Ensembl gene ENSG00000136381.
Subcellular location: Cytoplasm
Subcellular location (Human Protein Atlas): Cell Junctions; Cytosol
Pathways (Reactome):
Transport of small molecules: Iron uptake and transport
Gene Ontology:
Molecular function: iron-responsive element binding; mRNA regulatory element binding translation repressor activity; protein binding; RNA binding; 4 iron, 4 sulfur cluster binding
Biological process: intracellular iron ion homeostasis; mRNA stabilization; negative regulation of translation; osteoclast differentiation
Cellular component: cytoplasm; cytosol
Genetic constraint (gnomAD): Loss-of-function variants: 16 observed, 62.42 expected, observed/expected ratio (o/e) 0.26, 90% interval 0.17 to 0.39. The upper end of that interval is the gene's LOEUF score, 0.39, which puts it in group 1 of 6, group 1 being the genes least tolerant of losing a copy. Missense variants: 628 observed, 856.45 expected, observed/expected ratio (o/e) 0.73, 90% interval 0.69 to 0.78. Synonymous variants: 262 observed, 293.09 expected, observed/expected ratio (o/e) 0.89, 90% interval 0.81 to 0.99.
Homologues: Orthologues: chimpanzee IREB2 (99% identical), macaque IREB2 (99% identical), pig IREB2 (96% identical), mouse Ireb2 (94% identical), rat Ireb2 (93% identical), dog IREB2 (93% identical), rabbit IREB2 (92% identical), guinea pig IREB2 (80% identical), tropical clawed frog ireb2 (67% identical), zebrafish ireb2 (66% identical), Drosophila melanogaster Irp-1B (53% identical), Drosophila melanogaster Irp-1A (53% identical), and 1 more. Paralogues in human: ACO1 (56% identical), ACO2 (22% identical).
Diseases named in the same sentence as IREB2 in open-access papers:
IREB2 is named in the same sentence as 141 diseases in open-access papers, as found by Europe PMC text mining. Sharing a sentence is not in itself a finding about the gene and the disease. The quoted sentences say what the papers report.
iron deficiency (37 papers, 2009 to 2025). "During cellular iron deficiency, IREB2 and ACO1 induce iron acquisition and retention by stabilising mRNAs that encode iron uptake proteins such as TFRC while blocking translation of mRNAs that encode proteins involved in iron sequestration and egress." (PMID 34880854, 2021). "During iron deficiency, iron regulatory proteins (ACO1/IRP1, IREB2/IRP2) increase iron levels by binding to a small subset of mRNA transcripts that harbor an iron responsive element (IRE) to modulate their translation." (PMID 29291011, 2017).
lung carcinoma (22 papers, 2010 to 2025). "cBioPortal identified IREB2 alterations in 1.6% of lung cancers (primarily missense mutations/amplifications)." (PMID 41377765, 2025). "PheWAS confirmed chromosome 15 SNPs as jointly associated with respiratory traits and lung cancer, regulating IREB2, CHRNA3/5, HYKK, and PSMA4." (PMID 41377765, 2025). "Curcumin noticeably induced ferroptosis via activating autophagy in NSCLC, while the knockdown of IREB2 remarkably weakened curcumin-caused tumor suppressor ability in lung cancer cells." (PMID 36059676, 2022). "Accordingly, our results suggest that lower expression of IREB2 gene, in the presence of the minor allele of rs2568494 (beta parameter, −0.210), confers a higher risk of lung cancer (OR = 1.437)." (PMID 28181565, 2017). "Together, these results provide convincing evidence that SNPs in the nicotinic acetylcholine receptor locus on chromosome 15 modulate expression levels of IREB2 and, thus, implicate IREB2 expression levels in the individual risk for lung cancer." (PMID 28181565, 2017). "We confirmed the association between IREB2 gene and lung cancer and between FAM13A gene and COPD in Polish patients." (PMID 26310313, 2015). "This study design enabled us to determine the possible link between COPD and lung cancer patients related to IREB2 and FAM13A variants." (PMID 26310313, 2015). "Development of cancer models with Irp1−/− and Irp2−/− mice is expected to better define the roles of IRPs in cancer and to elucidate the molecular basis underlying the association of IRP2 (IREB2) genomic locus with susceptibility to lung cancer." (PMID 25120486, 2014). "SNPs in the chromosome 15 CHRNA3/CHRNA5/LOC123688/IREB2 region have been shown to have associations with lung cancer and COPD unrelated to AAT deficiency." (PMID 22356581, 2012). "In addition, when NFS1 is repressed, it consequently initiates the iron-responsive element binding protein 2 (IREB2/IRP2)-mediated iron-deficient response and makes lung cancer cells responsive to ferroptosis." (PMID 38660623, 2024). "IREB2 is located in the susceptibility locus of lung cancer." (PMID 34938740, 2021). "In addition, GWAS results illustrate that IREB2 has been shown to be associated COPD and the expression of its protein product IRP2 is altered in lung cancer patients carrying lung cancer." (PMID 34938740, 2021). "IREB2 has been previously reported to be associated with both chronic obstructive pulmonary disease and lung cancer, and a recent study suggests a stronger association for lung cancer than chronic obstructive pulmonary disease." (PMID 29486777, 2018). "A recent study also reported that the miRSNP rs1062980 may alter the expression of iron-responsive element binding protein 2 gene (IREB2) potentially through modulating the binding of miR-29a, and thereby modify risk of lung cancer." (PMID 29844858, 2018). "The IREB2 variants have been previously linked to COPD as well as lung cancer." (PMID 26310313, 2015). "The genotype AA of IREB2 rs2568494 was significantly more frequent among LC group (P = 0.0081; OR = 1.682), which suggested that this variant might increase the risk of lung cancer." (PMID 26310313, 2015). "In brief, IREB2 has previously been associated with smoking phenotypes (e.g., number of cigarettes a day, numbers of cigarettes previously smoked daily), parental illnesses such as lung cancer and chronic bronchitis, and psychiatric disorders like schizophrenia and bipolar disorder." (PMID 34775485, 2022). "Elevated IREB2 expression correlated with accelerated lung‐function decline in COPD but predicted improved prognosis in lung cancer B cells, whereas higher CD27+ B cell levels in COPD were associated with protumorigenic activity." (PMID 41377765, 2025). "Key genetic loci and genes, including IREB2, were implicated as potential drivers of COPD progression to lung cancer." (PMID 41377765, 2025).
lung carcinoma (continued). "Two‐step MR (FinnGen) further indicated that IREB2 mediates COPD‐to‐lung cancer progression (including LUAD and LUSC), supporting its role as a potential driver gene." (PMID 41377765, 2025). "Integration of COPD and lung cancer B cells identified five subsets, with IREB2 highest in activated B cells and lowest in regulated subsets." (PMID 41377765, 2025). "​Furthermore,​​ IREB2 polymorphisms, notably rs2568494, was associatde with COPD and lung cancer risk and reduced lung function." (PMID 41377765, 2025). "Elevated IREB2 expression in lung tissue and blood was positively associated with COPD, emphysema, chronic bronchitis, and lung cancer, but inversely with lung function; these results passed HEIDI test in lung but not blood." (PMID 41377765, 2025). "While most COPD GWAS suggest protective IREB2 mutations, we found novel IREB2 SNPs linked to lung cancer in COPD patients, implying its potential role as a driver gene in COPD progression to lung cancer." (PMID 41377765, 2025). "Two‐sample MR showed that higher IREB2 expression in lung and blood was negatively associated with COPD, emphysema/chronic bronchitis, and lung cancer, but positively with lung function." (PMID 41377765, 2025). "For example, the gene of Iron Responsive Element Binding Protein 2 (IREB2) is a key player in the Erastin-induced ferroptosis of HT-1080 fibrosarcoma cells and Calu-1 lung cancer cells." (PMID 37299036, 2023). "Consistently, multiple studies have shown the ectopic expression of ACO1 and IREB2 in several types of solid cancer, including lung cancer, breast cancer, and prostate cancer." (PMID 36059676, 2022). "The most common genes shared by these multimorbidities are IREB2 and CHRNA3, located in 15q25, a well-known region for association with COPD, lung cancer, and smoking." (PMID 34225788, 2021). "The current study aimed to determine the association of previously reported IREB2 and FAM13A SNPs with lung cancer and chronic obstructive pulmonary disease among two selected groups of Polish patients and smoking controls." (PMID 26310313, 2015). "The region on 15q25 contains the genes CHRNA3, CHRNA5, CHRNB4, AGPHD1, and IREB2, and numerous GWA have shown evidence of association of this region with COPD, emphysema, lung cancer, and smoking intensity." (PMID 26634245, 2015). "Genome-wide association studies have identified loci at 15q25 (IREB2) and 4q22 (FAM13A), associated with lung cancer (LC) and chronic obstructive pulmonary disease (COPD)." (PMID 26310313, 2015). "IREB2 is in strong linkage disequilibrium (LD) with nicotine receptor genes (CHRNA3 and 5) and it is this that led IREB2 to be investigated in relation to respiratory conditions such as chronic obstructive pulmonary disease and lung cancer." (PMID 26629341, 2015). "COPD cohorts showed high IREB2 expression correlating with lung cancer pathways." (PMID 41377765, 2025). "In addition, ACO1 and IREB2 were identified to be required for erastin-induced ferroptosis in lung cancer cells." (PMID 36059676, 2022). "When the IREB2 association was examined in the lung cancer cases without COPD (N = 369) compared to controls the results were comparable to those received for general lung cancer group (N = 468)." (PMID 26310313, 2015). "Genome-wide association studies (GWAS) showed that the IRP2 gene (IREB2) confers susceptibility to chronic obstructive pulmonary disease (COPD) and lies within a lung cancer-associated locus." (PMID 25120486, 2014). "Notably, while our findings position IREB2 as a driver of COPD‐to‐lung cancer progression, paradoxically, several reports suggest high IREB2 expression in established lung cancer may associate with improved prognosis." (PMID 41377765, 2025). "Intersection analysis identified core COPD–lung cancer genes (UBA7, ZDHH5, GMPPB, IREB2, PYGB), with emphysema‐specific IREB2 (lung) and PSMA4 (blood)." (PMID 41377765, 2025).
lung carcinoma (continued). "Cross‐validated SNPs rs16969968/rs12914385, cis‐regulatory hubs for COPD–lung cancer pathogenesis, colocalized with ρ‐HESS‐identified regions, mechanistically linking dysregulation of PSMA4, IREB2, CHRNA3, and CHRNA5 to disease etiology." (PMID 41377765, 2025). "In B cells, 138 DEGs were shared by IREB2+ and IREB2+CD27+ cells, and their signature predicted favorable prognosis in lung cancer and LUAD, suggesting IREB2 may suppress malignancy within B cells." (PMID 41377765, 2025). "High IREB2 correlated with improved lung cancer prognosis (nonsignificant in LUSC), high PSMA4 expression correlates with poor prognosis in lung cancer overall but demonstrates a favorable association in LUAD patients​." (PMID 41377765, 2025). "Despite potential importance, few studies explore IREB2 roles in COPD and lung cancer." (PMID 41377765, 2025). "​Critically, given differential IREB2 expression across COPD and lung cancer cell subtypes, its effects may extend beyond memory B cells." (PMID 41377765, 2025). "In the current study, the IREB2 locus was also examined in the lung cancer cases without COPD and the results just reflect the overall case-control relationship." (PMID 26310313, 2015). "Additionally, our findings indicate that IREB2 may exert stage‐ and cell type‐specific effects in COPD and lung cancer." (PMID 41377765, 2025). "Current evidence therefore highlights IREB2, but not PSMA4, as a candidate driver in COPD–lung cancer transition." (PMID 41377765, 2025).
colorectal cancer (15 papers, 2020 to 2026). A primary or metastatic malignant neoplasm that affects the colon or rectum. "Iron‐responsive element‐binding protein 2 (IREB2) is a principal regulator of iron metabolism, and miR‐19a suppresses ferroptosis of colorectal cancer cells by targeting IREB2." (PMID 41560416, 2026). "For example, OTUD1 in colorectal cancer cells promotes iron uptake mediated by TfR1 by stabilizing iron response element binding protein 2 (IREB2), which exacerbates ROS production and induces ferroptosis." (PMID 40535125, 2025). "MiR-19a suppresses ferroptosis in colorectal cancer by modulating iron metabolism and inhibiting the ferroptosis-inducing factor iron-responsive element-binding protein 2 (IREB2)." (PMID 39763590, 2024). "In clear cell renal carcinoma, colorectal carcinoma and intrahepatic cholangiocarcinoma, IREB2 affects tumor development through ferroptosis-related mechanism." (PMID 37978473, 2023). "Taken together, our results revealed miR-19a attenuates ferroptosis of colorectal cancer cells via suppressing IREB2." (PMID 35599631, 2022). "Furthermore, miR-19a inhibits ferroptosis in HT29 colorectal cancer cells by downregulating the iron sensor IREB2, resulting in less iron accumulation and therefore lower chance of ferroptosis occurring." (PMID 40806335, 2025). "A recent study found that miR-19a targets IREB2 to inhibit ferroptosis in colorectal cancer." (PMID 39872538, 2024). "MiR-19a suppresses the ferroptosis of colorectal cancer cells by targeting IREB2." (PMID 37238692, 2023). "miR-19a attenuates ferroptosis of colorectal cancer cells by suppression of IREB2." (PMID 35599631, 2022).
chronic obstructive pulmonary disease (13 papers, 2013 to 2025). A chronic and progressive lung disorder characterized by the loss of elasticity of the bronchial tree and the air sacs, destruction of the air sacs wall, thickening of the bronchial wall, and mucous accumulation in the bronchial tree. "For instance, m6A-modified circSAV1 promotes IREB2 mRNA translation, triggers ferroptosis in lung epithelial cells, and drives the progression of chronic obstructive pulmonary disease." (PMID 41105618, 2025). "Iron-responsive element-binding protein 2 (IRP2) has been implicated in the development and progression of chronic obstructive pulmonary disease (COPD), making IRP2 a powerful therapeutic target." (PMID 35624729, 2022). "In Early Chronic Obstructive Pulmonary Disease (ECOPD) cohort peripheral blood (n = 104), no significant IREB2/PSMA4 expression differences existed between controls and COPD, regardless of smoking status." (PMID 41377765, 2025).
microcytic anemia (12 papers, 2010 to 2024). Anemia in which the red blood cell volume is decreased. "Here, we describe a new NDCAMA patient with novel biallelic missense variants in IREB2, manifested as developmental delay, epilepsy, hypertonia, and microcytic anemia." (PMID 39587636, 2024). "Systemic deficiency of Irp2 in mice results in microcytic anemia, erythropoietic protoporphyria, neurodegeneration, and diabetes, which are clinically manifested by phenotypes of patients with bi-allelic loss-of-function variants in IREB2." (PMID 36978814, 2023). "Our study expands the understanding of Neurodegeneration, Early-onset, with Choreoathetoid Movements and Microcytic Anemia (NDCAMA) by reporting a further case involving biallelic missense variants in the IREB2 gene." (PMID 39587636, 2024). "While Ireb2(-/-) mice develop microcytic anemia, deletion of Fbxl5 in murine hematopoietic stem cells leads to impaired hematopoiesis due to Ireb2 overexpression and subsequent iron overload." (PMID 33679722, 2020).
breast carcinoma (8 papers, 2017 to 2025). "Iron-responsive element binding protein 2 (IREB2) is overexpressed in breast cancer, and IREB knockout can delay the growth of breast tumors." (PMID 39225900, 2024).
colon cancer (6 papers, 2020 to 2024). "Promote the stability of IREB2 protein and activate the expression of its downstream TFRC gene, resulting in intracellular Fe2+ aggregation and increased ROS level, and eventually raise colon cancer cells’ susceptibility to ferroptosis." (PMID 38666028, 2024). "Moreover, it has been reported that in colon cancer cells, the Ireb2 gene is circadianly transcribed through BMAL1:CLOCK, engendering Ireb2 mRNA and IREB2/IRP2 protein oscillations that subsequently regulate Tfrc stability in a rhythmic fashion." (PMID 38773499, 2024). "For Ireb2, the mRNA phase — maximal abundance around ZT10 — was in principle compatible with the BMAL1:CLOCK regulation reported from colon cancer cells." (PMID 38773499, 2024).
emphysema (6 papers, 2011 to 2025). "In UK National Registry of AATD, IREB2 SNP rs2568494 was shown to be significantly associated with emphysema, and this effect appeared to be more prominent in males." (PMID 26629341, 2015). "Replication in another cohort of AAT deficient subjects from the UK showed that a SNP in IREB2 was also associated with emphysema in men." (PMID 22356581, 2012). "The SNP rs2568494 in IREB2 was significantly associated with emphysema in the male subgroup, the A allele conferring an odds ratio and 95% confidence interval (OR and 95% CI) of disease of 2.67 (1.10-6.51, p = 0.03)." (PMID 22356581, 2012).
Parkinson disease (6 papers, 2006 to 2025). A progressive degenerative disorder of the central nervous system characterized by loss of dopamine producing neurons in the substantia nigra and the presence of Lewy bodies in the substantia nigra and locus coeruleus. "The brain protein IREB2 is associated with Alzheimer’s disease, whereas the brain protein MAOB is associated with both Alzheimer’s and Parkinson’s diseases." (PMID 35259090, 2022). "Three of these genes (EN2, IREB2, and NGFB) are currently associated only with high level or general biological process categories that might or might not be related to Parkinson's disease." (PMID 16762065, 2006).
hepatocellular carcinoma (5 papers, 2022 to 2024). A malignant tumor that arises from hepatocytes. "KLF14 was significantly downregulated in hepatocellular carcinoma (HCC), correlating with poor prognosis, and inhibits the proliferation of HCC cells by modulating cellular iron metabolism via the repression of Iron-responsive element-binding protein 2 (IRP2)." (PMID 39518098, 2024).
iron metabolism disorder (5 papers, 2021 to 2025). "Therefore, abnormal IREB2 expression or function may lead to iron metabolism disorder." (PMID 34938740, 2021). "In addition, overexpressing IREB2 increased IL-1β, IL-6, and TNF-α, promoting HFD-induced metabolic disorders, hepatic steatosis, and inflammation." (PMID 39910919, 2025).
asthma (3 papers, 2020 to 2025). "Gene Set Enrichment Analysis (GSEA) revealed IREB2 in LUAD positively regulates Hedgehog/TGF‐β pathways but negatively regulates asthma/oxidative phosphorylation." (PMID 41377765, 2025).